EPYC (epiphycan)
Description:
May have a role in bone formation and also in establishing the ordered structure of cartilage through matrix organization.
Synonyms: PG-Lb; DSPG3; PGLB; SLRR3B
Tractability: Antibody: UniProt places it where antibodies can reach, with medium confidence; UniProt predicts a signal peptide or a membrane-spanning region; its Gene Ontology location is reachable by antibodies, with medium confidence.
Gene: Protein-coding gene on chromosome 12 (90,963,682 to 91,005,026, reverse strand). Ensembl gene ENSG00000083782.
Subcellular location: Secreted, extracellular space, extracellular matrix
Gene Ontology:
Molecular function: glycosaminoglycan binding
Biological process: articular cartilage development; bone development; female pregnancy
Cellular component: extracellular matrix; gel phase of interstitial matrix
Genetic constraint (gnomAD): Loss-of-function variants: 19 observed, 19.96 expected, observed/expected ratio (o/e) 0.95, 90% interval 0.66 to 1.4. The upper end of that interval is the gene's LOEUF score, 1.4, which puts it in group 5 of 6, group 1 being the genes least tolerant of losing a copy. Missense variants: 281 observed, 310.6 expected, observed/expected ratio (o/e) 0.9, 90% interval 0.82 to 1. Synonymous variants: 109 observed, 117.84 expected, observed/expected ratio (o/e) 0.93, 90% interval 0.79 to 1.09.
Homologues: Orthologues: chimpanzee EPYC (99% identical), macaque EPYC (98% identical), dog EPYC (95% identical), pig EPYC (94% identical), rabbit EPYC (92% identical), guinea pig EPYC (89% identical), mouse Epyc (82% identical), rat Epyc (82% identical), tropical clawed frog epyc (66% identical), zebrafish epyc (52% identical). Paralogues in human: OGN (37% identical), LINGO3 (23% identical), ECM2 (22% identical), PRELP (21% identical), LUM (20% identical), FMOD (20% identical), LINGO4 (20% identical), OMD (20% identical), KERA (19% identical), OMG (13% identical).
Diseases named in the same sentence as EPYC in open-access papers:
EPYC is named in the same sentence as 31 diseases in open-access papers, as found by Europe PMC text mining. Sharing a sentence is not in itself a finding about the gene and the disease. The quoted sentences say what the papers report.
ovarian carcinoma (4 papers, 2016 to 2024). A malignant neoplasm originating from the surface ovarian epithelium. "EPYC exhibits high expression in ovarian cancer and is significantly associated with both OS and disease-free survival (DFS) in patients with ovarian cancer." (PMID 37351109, 2023). "To explore the function of EPYC in ovarian cancer, we interfered the expression of EPYC in SKOV3 cells by EPYC-siRNAs." (PMID 34888227, 2021). "The results showed that the expression of EPYC in metastatic ovarian cancer was higher than primary ovarian cancer, and that in primary cancer was higher than normal ovaries." (PMID 34888227, 2021). "In the present study, we found that EPYC was the most overexpressed gene in metastatic ovarian cancer tissues than ovarian cancer by analyzing the GSE38734 raw data." (PMID 34888227, 2021). "Using the TCGA database, we found out that EPYC gene expression was associated with late FIGO staging of ovarian cancer, without correlation with age, pathological grade, or death." (PMID 34888227, 2021). "EPYC expression was significantly up-regulated in ovarian cancers (p=0.02)." (PMID 34888227, 2021). "Thus, we aimed to clarify the role of EPYC in progression of ovarian cancer (OC), and further analyze the molecular mechanisms implicated in tumorigenesis." (PMID 34888227, 2021). "We used siRNAs to interfere the expression of EPYC in ovarian cancer cell line SKOV3." (PMID 34888227, 2021). "Expression of EPYC with clinicopathological parameter of ovarian cancers from the TCGA database." (PMID 34888227, 2021). "It indicates that EPYC may play an important role in the malignant progression of ovarian cancer." (PMID 34888227, 2021). "However, the function and mechanism of EPYC in ovarian cancer are still unknown." (PMID 34888227, 2021). "Therefore, we speculated that EPYC in ovarian cancer might regulate the expression of SNAI2 by activating the TGF-β/PI3K/AKT signaling pathway, and promoted the occurrence of EMT and invasion and metastasis of ovarian cancer." (PMID 34888227, 2021).
posterior amorphous corneal dystrophy (4 papers, 2011 to 2024). Posterior amorphous corneal dystrophy (PACD) is a very rare form of stromal corneal dystrophy characterized by irregular amorphous sheet-like opacities in the posterior corneal stroma and in Descemet membrane and mildly impaired vision. "Haploinsufficiency of EPYC is associated with posterior amorphous corneal dystrophy, thereby resulting in the corneal opacification, thickness, and curvature, iris coloboma and atrophy, and iridocorneal adhesions." (PMID 28860661, 2017). "DCN is also lost together with keratocan (KERA), lumican (LUM), and epiphycan (EPYC) in posterior amorphous stromal dystrophy (PACD), which is characterized by stromal opacities in the first decade of life." (PMID 39394466, 2024). "A human genome-wide linkage analysis of posterior amorphous corneal dystrophy identified a region of human chromosome 12 that is orthologous to a Mcs6 region that contains genes DCN, LUM, KERA, and EPYC." (PMID 21625632, 2011).
breast carcinoma (3 papers, 2016 to 2024). "We propose that CACNG4, PKMYT1, and CHRNA6 hold promise as potential targets for both the diagnosis and treatment of breast cancer, while EPYC has the potential to be used only as an effective diagnostic biomarker." (PMID 38291367, 2024). "Similarly, the results of pan-cancer analysis suggested that EPYC was aberrantly expressed in many tumors (breast cancer, colon adenocarcinoma, lung adenocarcinoma, etc.)in addition to PC, whereas the roles of EPYC in these tumors were still obscure." (PMID 38184732, 2024). "Furthermore, the COSMIC database analyzed the mutations of the CACNG4, PKMYT1, EPYC, and CHRNA6 genes in breast cancer." (PMID 38291367, 2024). "Through bioinformatics analysis and qRT-PCR validation, we confirmed the upregulation of CACNG4, PKMYT1, EPYC, and CHRNA6 in breast cancer." (PMID 38291367, 2024). "Based on qRT-PCR analysis conducted on 55 breast cancer patients and normal cases, it was observed that CACNG4, PKMYT1, EPYC, and CHRNA6 mRNA exhibited significantly higher expression levels in breast cancer tissues (BCT) compared to non-tumoral adjacent tissues (NTAT) (P < 0.0001)." (PMID 38291367, 2024).
osteoarthritis (3 papers, 2020 to 2025). A noninflammatory degenerative joint disease occurring chiefly in older persons, characterized by degeneration of the articular cartilage, hypertrophy of bone at the margins and changes in the synovial membrane. "EPYC has been implicated in critical roles across a spectrum of human diseases, including osteoarthritis, high myopia, rheumatoid arthritis, among others." (PMID 40075313, 2025). "The silencing of EPYC and the overexpression of KLF9 are associated with the occurrence of osteoarthritis and immunocyte infiltration." (PMID 35902862, 2022). "Opticin null mice showed protection against osteoarthritis and it was found that these mice had increased levels of lumican and epiphycan, and decreased levels of fibromodulin." (PMID 32764753, 2020). "EPYC and KLF9 can be viewed as feature genes for osteoarthritis." (PMID 35902862, 2022).
pancreatic cancer (3 papers, 2024 to 2025). "The expression of five key genes (MMP11, COL10A1, SERPINE1, COL11A1, and EPYC) in normal pancreatic and pancreatic cancer cell lines were detected using qPCR." (PMID 38572434, 2024). "Moreover, previous research has shown that EPYC can promote the proliferation of pancreatic cancer through the PI3K-AKT signaling pathway, highlighting its potential as a prognostic biomarker for the disease." (PMID 40075313, 2025). "High expression of EPYC, ANKRD22, ARNTL2, DSG3, KRT7, PRSS3 and MET predict poor prognosis of pancreatic cancer patients." (PMID 38184732, 2024).
myopia (2 papers, 2009 to 2012). "Extracellular matrix components such as collagen type I alpha 1 (COL1A1), collagen type II alpha 1 (COL2A1), lumican (LUM), decorin (DCN) and epiphycan (EPYC or DSPG3) have been previously assessed for genetic associations with myopia." (PMID 23077567, 2012). "In summary, our results suggest that both OPTC and EPYC are unlikely to play a major role in high myopia." (PMID 19844586, 2009). "The purpose of this study was to test whether mutations in the two members of the class III SLRPs, opticin (OPTC) and dermatan sulfate proteoglycan 3 (EPYC), are responsible for high myopia." (PMID 19844586, 2009). "However, an evaluation of the coding and adjacent intronic sequences of EPYC has not reported in patients with high myopia thus far." (PMID 19844586, 2009).
Blindness (1 paper, 2017). Blindness is the condition of lacking visual perception defined as a profound reduction in visual perception. "Of note, MD can cause lymphocyte infiltration of the iris, pupils in unequal size, and blindness, and EPYC was currently identified down-regulated in MDV-chickens, so it was considered a candidate promising gene affecting iris lesion in MD chickens." (PMID 28860661, 2017).
breast tumors (1 paper, 2024). "Paired t-tests comparing the gene expression profiles of CACNG4, PKMYT1, EPYC, and CHRNA6 between breast tumors and normal tissues revealed an almost 5.55-fold, 2.31-fold, 2.32-fold, and 2.14-fold increase in breast tumors, compared to normal tissues, respectively." (PMID 38291367, 2024).
corneal dystrophy (1 paper, 2024). The term corneal dystrophy embraces a heterogeneous group of bilateral genetically determined non-inflammatory corneal diseases that are usually restricted to the cornea. "Studies have shown that insufficient expression of EPYC can lead to corneal dystrophy and hearing loss." (PMID 38291367, 2024).
ductal carcinoma (1 paper, 2011). "Mcs6 human orthologous transcripts that have been reported as differentially expressed between non-diseased breast tissue and ductal carcinoma tissue encode for two phosphatases (DUSP6, PPP1R12A), a proteoglycan (EPYC), a redox regulator (TXNRD1), and two uncharacterized proteins (ALX1, ZDHHC17)." (PMID 21625632, 2011).
Hernia (1 paper, 2020). "The results pointed out ACAN, MMPs, COLs, EPYC, VIT, CCBE1 and LGALS3 genes as strong candidates to trigger umbilical hernias in pigs, because they are involved in hernia related biological processes since the embryogenesis." (PMID 32379844, 2020).
mucinous cystadenocarcinoma (1 paper, 2021). An invasive adenocarcinoma characterized by cystic changes and the presence of malignant glandular cells which contain intracytoplasmic mucin. "From the HPA website, we learned that EPYC protein was barely expressed in normal ovarian tissue (0/3), but could be moderately expressed in a third of OC tissues (4/12, 2 serous cystadenocarcinomas and 2 mucinous cystadenocarcinomas)." (PMID 34888227, 2021).
osteosarcoma (1 paper, 2025). A usually aggressive malignant bone-forming mesenchymal neoplasm, predominantly affecting adolescents and young adults. "The differential analysis showed that in the osteosarcoma group, the expression of EPYC and PANX3 was obviously elevated, whereas the expression of CD36, CLDN11 and STOM was markedly decreased." (PMID 40075313, 2025). "In our study, we found that EPYC plays a crucial role in the malignant progression of osteosarcoma and serves as an independent predictor of poor prognosis." (PMID 40075313, 2025). "This study identifies EPYC, CLDN11, and STOM for the first time as biomarkers associated with the prognosis of osteosarcoma." (PMID 40075313, 2025). "The findings indicate that EPYC plays a central role in the malignant progression of osteosarcoma and serves as an independent predictor of poor prognosis." (PMID 40075313, 2025). "The five biomarkers (CD36, CLDN11, EPYC, PANX3, and STOM) were screened to construct an AAMRGs risk model with prognostic value, providing a new reference for the prognosis and treatment of osteosarcoma." (PMID 40075313, 2025). "Furthermore, EPYC expression levels in osteosarcoma tissue are significantly higher than those in adjacent non-tumor tissue." (PMID 40075313, 2025). "Validation of gene expression through public databases and RT-qPCR results showed significant upregulation of EPYC and PANX3 in osteosarcoma samples, while CD36, CLDN11, and STOM were significantly downregulated." (PMID 40075313, 2025). "In order to develop a risk model with the optimal prognostic predictive capacity of these DE-AAMRGs in osteosarcoma patients, we performed univariate Cox analysis and utilized the LASSO method to select a panel of five biomarkers (CD36, CLDN11, EPYC, PANX3, and STOM)." (PMID 40075313, 2025). "The IHC analysis displayed that osteosarcoma tissues express significantly higher levels of EPYC and PANX3 compared to adjacent non-tumorous tissues." (PMID 40075313, 2025). "The roles of PANX3 and CD36 are well established; however, the specific functions of EPYC, CLDN11, and STOM in osteosarcoma remain unclear." (PMID 40075313, 2025). "Additionally, EPYC expression levels were elevated in osteosarcoma tissues compared to adjacent non-tumorous tissues." (PMID 40075313, 2025). "However, the research concerning the involvement of EPYC in osteosarcoma is non-existent." (PMID 40075313, 2025).
prostate carcinoma (1 paper, 2022). A carcinoma that arises from epithelial cells of the prostate gland. "Moreover, NSAIDS drugs, as the first-line treatment for OA, have been proven effective in curbing the expression of EPYC in prostate cancer cells, but their effects on EPYC gene expression in OA articular chondrocytes should be further explored." (PMID 35902862, 2022).
serous ovarian cancer (1 paper, 2021). "However, when using the online tool Kaplan-Meier Plotter website, which includes 1435 OC patients, we found that EPYC expression was associated with poor prognosis of serous ovarian cancer, with cutoff value 23 used in analysis." (PMID 34888227, 2021).
Umbilical hernia (1 paper, 2020). Protrusion of abdominal contents through a defect in the abdominal wall musculature around the umbilicus. "From this set of genes, we highlight KRT14 (Keratin 14), CCBE1, ACAN, Desmoglein 2 (DSG2) and EPYC, which were more enriched in the anatomic development process in the gene network and were upregulated in animals affected by umbilical hernia." (PMID 32379844, 2020). "The results pointed out ACAN, MMPs, COLs, EPYC, VIT, CCBE1 and LGALS3 as strong candidates to trigger umbilical hernias in pigs since they act in the extracellular matrix remodeling and in the production, integrity and resistance of the collagen." (PMID 32379844, 2020).
cancer (5 papers, 2019 to 2024). A tumor composed of atypical neoplastic, often pleomorphic cells that invade other tissues. "The overexpression of two of the OCs, EPYC and NELL2, were associated with minor changes in the cancer transcriptome (≤ 5 differentially expressed transcripts)." (PMID 30820027, 2019). "However, there have been very few studies on the role of EPYC in cancer." (PMID 38291367, 2024). "However, epiphycan (EPYC), as a member of the SLRPs family, its biological function in cancer has not been confirmed." (PMID 34888227, 2021).
tumor (5 papers, 2019 to 2025). "Nonetheless, the specific function of EPYC within the context of tumor biology remains to be elucidated." (PMID 40075313, 2025). "Furthermore, we also labeled the final candidate gene EPYC separately in volcano maps, and the results showed that EPYC was up-regulated in tumor tissues compared with that in normal tissues." (PMID 38184732, 2024). "To further confirm the role of EPYC in PC, we queried EPYC data in relevant online databases (GEPIA, HPA, ULCAN), and the results showed that EPYC functioned as an oncogene to be highly expressed in tumor tissues and had a significant impact on the survival prognosis." (PMID 38184732, 2024). "The common upregulated genes in metastasis and primary tumor include epiphycan (EPYC), collagen type X alpha chain 1 (COL10A1), fibronectin type III domain containing 1 (FNDC1) and podocan-like protein I (PODNL1), which are mainly extracellular matrix related genes." (PMID 31600962, 2019).
EPYC also shares sentences with these, for which no sentence is quoted: infection (2 papers); Atrophy (1); colon adenocarcinoma (1); deafness (1); Ehlers-Danlos syndrome (1); gastric cancer (1); hearing loss (1); infectious disease (1); iris coloboma (1); lung adenocarcinoma (1); rheumatoid arthritis (1); serous cystadenocarcinoma (1); vitamin D deficiency (1).